TOP1 (DNA topoisomerase I)
Diseases named in the same sentence as TOP1 in open-access papers (continued):
Sharing a sentence is not in itself a finding about the gene and the disease.
tumor (continued). "TOP1 inhibition by Topotecan (TPT) or Camptothecin (CPT) has shown anti-tumor effects in xenograft models and clinical trial patients." (PMID 39156107, 2024). "The correlations between TOP1 and specific pathways, such as tumor proliferation and DNA repair, were analyzed using the online tool." (PMID 39156107, 2024). "TOP1 was shown to regulate tumor-promoting inflammation and programmed death-ligand 1 (PD-L1) production in a cGAS-dependent manner." (PMID 39156107, 2024). "DXd, as the cytotoxic payload of I1‐DXd, is a DNA topoisomerase I (TOP1) inhibitor with higher anti‐tumor activity and cell membrane permeability than SN‐38." (PMID 38874532, 2024). "The cell-injected mice were maintained on a normal diet, and the effect of TOP1 inhibition on tumor formation was assessed." (PMID 39156107, 2024). "We show that combining the TOP1 inhibitor irinotecan with the BRD4 inhibitor JQ1 synergistically kills the tumor cells in the PDX model of both tumor types." (PMID 37831776, 2023). "Collectively, our study highlights the potential of PARP as a therapeutic target across different pediatric tumor types and suggests combination with TOP1 inhibition to improve efficacy." (PMID 37020198, 2023). "CPT has been recognized as a potent antiproliferative agent toward various tumor cells, due to its unique affinity for binding with DNA Topoisomerase I of tumor cells, inducing protein-DNA breakage." (PMID 37855596, 2023). "And vice versa, overexpression of Tdp1 in tumor cells leads to a decrease in sensitivity to Top1 inhibitors." (PMID 36653585, 2023). "Next, we conducted IHC analysis on the excised tumor tissues to measure the protein levels of Ki67, TOP1, and TOP2." (PMID 37088855, 2023). "Topoisomerase inhibitors are an important class of anti-tumor drugs since tumor cells have abnormally high expression of TOP1 and TOP2." (PMID 37386467, 2023). "Two main facts have to be taken into consideration: (i) that Ki67 is a tumor marker with different roles expressed during the whole cell cycle (except G0), and (ii) that irinotecan targets DNA topoisomerase I, disrupting DNA synthesis and cell replication." (PMID 36829677, 2023). "The anti-tumor (20R)-22E-24-ethylcholesta-4,22-dien-3-one was isolated from the stems and leaves of adlay, and had pro-apoptotic effects on three types of tumor cells, as well as having an inhibitory effect on DNA topoisomerase I." (PMID 35956759, 2022). "In conclusion, alongside its essential role in relieving DNA torsional stress, TOP1 also drives mutagenesis in somatic and germline contexts, relevant to neoplasia, inherited disease and human variation." (PMID 35140396, 2022). "Our analysis of the relationship of expression showed that the postoperative level of TOP1 gene is higher in patients with a large primary tumor node (1.34 ± 0.57) than in patients in the T1–2 group (0.85 ± 0.28), with p = 0.02." (PMID 35204496, 2022). "The principle of camptothecin and its derivatives is to selectively act on DNA topoisomerase I (Topo I), stabilize DNA Topo I complex, block DNA replication and transcription, and lead to tumor cell apoptosis." (PMID 36686767, 2022). "This is coherent with the results of our dataset analysis, in which we found they showed a strong correlation with the tumor phenotype, with TOP1 and PDIA4 positively correlating and OGN being negatively correlated." (PMID 35197484, 2022). "The anti-tumor mechanism of PTE was further explored by detecting the effect of PTE on the DNA repair pathway mediated by Top1/tdp1 in vivo." (PMID 34439157, 2021). "Targeting circIPO11 and TOP1 has synergistic antitumor effects on HCC patient-derived tumor cells (PDC) models." (PMID 34649567, 2021). "Another approach being explored in our NCI clinic is to combine ATR inhibitors with tumor-targeted DNA damaging agents, such as tumor-targeted TOP1 inhibitors (TTT is)." (PMID 34572827, 2021).
tumor (continued). "WB assay results indicated that the protein contents of Top1 and Tdp1 in animal tumor tissues were decreased significantly, especially in the positive control group and the high-concentration PTE treatment group." (PMID 34439157, 2021). "In the tumor cells, SN-38 can target topoisomerase I (Top1)-DNA covalent reaction intermediates and reversibly stabilize the Top1-DNA-SN-38 complex." (PMID 35582377, 2021). "A low tumor mutation burden (4–7 muts/Mb) characterized most of the testicular LCT except the peculiar metastatic case with a B4GALT5:TERT fusion and TOP1 and CCND3 amplifications that exhibited 11 muts/Mb." (PMID 33741265, 2021). "We observed a similar dose-response curve for TOP1 protein inhibition in HCT116 tumor tissue after CBX-12 administration for 4 days in vivo, with an IC50 of 30 nM." (PMID 34316708, 2021). "Exatecan is a derivative of the TOP1 inhibitor camptothecin, with improved potency and robust efficacy across a broad range of tumor models in vitro and in vivo." (PMID 34316708, 2021). "Using these data, we were able to accurately predict the levels of exatecan derived from CBX-12 in tumor, with dosing of CBX-12 resulting in both a dose-dependent increase in exatecan and decrease in TOP1 protein levels in the tumor." (PMID 34316708, 2021). "In conclusion, we have described a new approach for delivering the potent TOP1 inhibitor exatecan selectively to tumor cells in an antigen-independent manner via conjugation to a variant of pHLIP." (PMID 34316708, 2021). "Nowadays, Topoisomerase 1 (Top1) enzyme is an important target of anti-tumor drugs, and Top1 inhibitors are widely used in clinical practice, the main chemotherapeutic drugs targeting Top1 were camptothecin (CPT) and its derivatives." (PMID 34439157, 2021). "Following incubation for 24 h in HCT116 tumor cells and rat bone marrow cells in vitro, unconjugated exatecan inhibited similar dose-response curves for TOP1 protein levels, with IC50s of 24.8 nM and 27.3 nM, respectively." (PMID 34316708, 2021). "Consequently, TDP1 activity may be a possible cause of tumor resistance to TOP1 inhibitors." (PMID 34768766, 2021). "Copy number variations of the Top1 gene were extensively investigated in normal mucosa and tumor tissue samples from 50 CRC patients." (PMID 35582377, 2021). "PTE has a more stable structure and superior pharmacokinetic properties; thus, it has a better anti-tumor effect in vivo with a higher ability to inhibit Top1 and Tdp1." (PMID 34439157, 2021). "Camptothecin and related drugs, including irinotecan, were designed to inhibit tumor cell proliferation by trapping Top1 on the DNA to stop the DNA replication process." (PMID 33062672, 2020). "Polymeric FPs such as F10 and CF10 that are more directly converted to FdUMP and FdUTP than 5-FU display improved anti-tumor activity and reduced systemic toxicities through dual targeting of TS and Top1." (PMID 32751071, 2020). "We tested the independence of ABCG2/TOP1 status in multivariable models including tumor site, MSI status, mucinous histology, and BRAF and KRAS mutation status (without interaction terms)." (PMID 32326511, 2020). "SG affects tumor growth via its SN-38 payload, which inhibits topoisomerase 1 (TOP1) through stabilization of the TOP1/DNA complex." (PMID 33196706, 2020). "The results showed that the GBM patient tumor WCEs exhibited a greater range of TOP1 expression and activity than TDP1." (PMID 31547492, 2019). "The genes most frequently showing CNGs in HAS tumour tissues were TOP1 (50.0%), STK4 (45.5%), CDKN1B (40.9%), H3F3A (36.4%), MYC (22.7%), CCNE1 (22.7%), NFKBIA (22.7%), VEGFA (18.2%), CCND3 (13.6%), and E2F1 (13.6%)." (PMID 30989433, 2019). "The new hybrid molecule showed a potency superior to both HDAC inhibitor SAHA and Top1 inhibitor Irinotecan, increased antitumor activity and very high tolerability in in vivo human tumor models with respect to SAHA and Topotecan." (PMID 30300374, 2018).
tumor (continued). "Increasing evidences demonstrate that TOP1 protein level, gene copy number, and mRNA expression are significantly correlated to unfavorable prognosis in most types of tumor." (PMID 28355294, 2017). "TOP1 plays a key role in cellular genetic processes, particularly modulating DNA topology, which is essential to proliferation of tumor cells." (PMID 28355294, 2017). "Camptothecin (CPT), a topoisomerase I (TOP1) inhibitor, exhibits anti-tumor activity against a wide range of tumors." (PMID 27220325, 2016). "High tumor Top1 protein expression was found to correlate significantly with therapeutic benefit from irinotecan." (PMID 27029323, 2016). "Clearly, more studies on the TOP1 mutations that affect these inhibitory SUMOylations are needed to establish a connection between tumor pathogenesis and a dysfunction in the regulation of TOP1 activity in human cells." (PMID 27181710, 2016). "DNA topoisomerase I (TOP1) levels of several human neoplasms are higher than those of normal tissues." (PMID 26207989, 2015). "Consistent with our goal to create a long-acting Top1 inhibitor, tumor growth suppression and complete regression continued for weeks after administration of the last etirinotecan pegol dose in all tumor models, even when only a single dose was administered." (PMID 25228368, 2014). "In the tumor samples, TOP1 signals ranged from 1.33 to 6.72 per nucleus with a median of 3.17 signals while the TOP1/CEN-2 ratio ranged from 1.01 to 3.39 with a median of 1.92." (PMID 23577133, 2013). "Of the 309 unique, validated mutations identified through sequencing of the TCGA GBM tumor samples, CTNNB1, EP300, STAT3, and TOP1 also appear in the 50-gene subnetwork signature." (PMID 24068912, 2013). "Due to inadequate tumor material or failed IHC analysis 315 cases were excluded, which resulted in available Top1 data from 1,313 tumor samples (81%)." (PMID 24400218, 2013). "Other studies have investigated the protein levels of Top1 in primary tumor CRC tissue by Immunohistochemistry (IHC)." (PMID 24400218, 2013). "Baseline Top1 levels in both patient tumor and PBMC samples show similarly large variation as that measured in xenografts." (PMID 23284638, 2012). "Determination of Top1 baseline levels in tumor biopsy extracts from six patients enrolled in clinical trials at the NCI showed 4 of 6 patients had Top1 levels within 1 SD of the mean." (PMID 23284638, 2012). "We have developed and validated a two-site enzyme chemiluminescent immunoassay for quantifying Top1 levels in tumor biopsies." (PMID 23284638, 2012). "Top1 concentrations for individual patients were determined by averaging three different protein loads for each tumor extract." (PMID 23284638, 2012). "Only values above the lower limit of quantitation (LLQ) were reported; patient baseline tumor biopsy Top1 levels ranged from 0.37 to 3.79 ng/mL/μg biopsy protein." (PMID 23284638, 2012). "Colo829 and HCT 116 xenograft models provide data supporting the link between Top1 levels, decrease in Top1 upon treatment, γH2AX induction (unpublished data) and tumor response." (PMID 23284638, 2012). "It has been proposed that CPT-induced Top1-DNA covalent adducts arrest the advancing replication forks, resulting in tumor cell death as well as DNA damage responses including activation of NF-κB." (PMID 22396773, 2012). "Accuracy was evaluated by spike/recovery of pure recombinant Top1 (rTop1) standards in tumor biopsy extracts and by analysis of dilution linearity of intrinsic Top1 in xenograft samples." (PMID 23284638, 2012). "The strategy is validated by the observation that amongst these molecules are several known Top1 inhibitors and agents cytotoxic against human tumour cell lines." (PMID 21966440, 2011). "As an additional test, the 5 compounds with confirmed Top1 inhibitory activity have also been tested for cytotoxicity against the NCI panel of 60 human tumour cell lines." (PMID 21966440, 2011).
tumor (continued). "Lam-D is a potent TOP1 inhibitor that has proven to be effective in treating multi-drug resistant tumor cell lines." (PMID 22113577, 2011). "This is the first time, to our knowledge, that the genomic variations of Top1 were studied in a variety of tumour and normal samples." (PMID 16983402, 2006). "Looking for a cellular model able to provide clues and tracks about the functional polymorphisms of the TOP1 gene, we decided to use the National Cancer Institute (NCI) panel of 60 human tumour cell lines." (PMID 16983402, 2006). "We previously suggested that the inhibition of TDP2 combined with a TOP1 inhibitor and chain-terminating nucleoside analogs may be an effective strategy for tumor treatment." (PMID 40155951, 2025). "Human DNA topoisomerase I (Topo I) is an essential enzyme in regulating DNA supercoiling during transcription and replication, and it is an important therapeutic target for anti-tumor agents." (PMID 39124952, 2024). "Conversely, a low level of TOP1 inhibits tumour cell growth." (PMID 39735605, 2024). "On the other hand, suppression of Tdp1 activity may increase the sensitivity of tumor cells to Top1 inhibitors, potentiating their effects." (PMID 38139858, 2023). "It is well known that Tdp1 is involved in the development of tumor resistance to Top1 inhibitors." (PMID 38139858, 2023). "Furthermore, the combinations of ATR and TOP1 inhibitors can augment tumor inflammation in STING‐low SCLC." (PMID 35957613, 2023). "Consequently, TOP1-ADC is an effective approach to enhance the anti-tumor activity of both the monoclonal antibody and the TOP1 inhibitor." (PMID 36015333, 2022). "Interestingly, Topotecan, a clinically used Top1 poison, can activate dendritic cells of tumour-bearing mice as exosomes released by the treated tumours are incorporated by dendritic cells, which then triggers the cGAS/STING signalling pathway." (PMID 36114513, 2022). "We noticed that TOP1 was also highly expressed in HCC tumor tissues." (PMID 34649567, 2021). "Topoisomerase 1 (Top1) inhibitor is an effective anticancer drug, but several factors limit its clinical application such as drug inactivation, tyrosyl-DNA phosphodiesterase 1 (Tdp1)-mediated tumor drug resistance, and its toxicity." (PMID 34439157, 2021). "Moreover, GLI1 is also highly expressed in HCC tumor tissues and liver CSCs, and TOP1 expression levels positively correlate with the metastasis, recurrence and survival of HCC patients." (PMID 34649567, 2021). "At the same time, the mRNA expression of Top1 and Tdp1 in tumor tissues was inhibited." (PMID 34439157, 2021). "Convincing evidence exists from preclinical studies that the ratio of Tdp1/Top1 activity influences cellular sensitivity to Top1 inhibitors, and that the suppression of Tdp1 activity leads to an increase in the sensitivity of tumor cells to CPTs." (PMID 31878088, 2019). "This dual targeting of TS/Top1 by F10 results in potent anti-tumor activity, which we have demonstrated occurs in multiple pre-clinical models of AML, acute lymphocytic leukemia, prostate cancer, glioblastoma, colorectal cancer, and pancreatic ductal adenocarcinoma." (PMID 31930190, 2019). "It should be borne in mind that TOP1 inhibitors and other drugs can cause anomalous increases in CMV reporter-controlled expression of luciferase and GFP, potentially confounding the interpretation of tumor imaging studies and pre-clinical drug testing." (PMID 24516563, 2014). "In this critical context, it could be of great interest to examine the expression of BRCA1 that may function as a potential regulator of TOP1 expression and therefore be determinant for the efficiency of the anti-tumour treatment." (PMID 23805307, 2013).
tumor (continued). "Tumor response and biomarkers for Top1 inhibitors in topotecan-responsive xenograft models." (PMID 23284638, 2012). "Using each individual tumor as its own control, as is frequently done in early-stage clinical trials, may minimize the effect of individual differences in baseline Top1 levels." (PMID 23284638, 2012). "As part of method validation, we also demonstrated the ability to measure baseline Top1 levels in 18-gauge needle tumor biopsies collected from patients in clinical trials at the NCI following standard operating procedures established for the clinical poly(ADP-ribose) immunoassay." (PMID 23284638, 2012). "Lkb1 is a known tumor suppressor and a negative regulator of the mTOR/Insulin pathway, which has important roles in autophagy and nutrient sensing, while the Camptothecins function as DNA Topoisomerase 1 (Top1) inhibitors." (PMID 21909362, 2011). "Although none of our tested compounds displays high cytotoxic activity in human tumour cell lines, our study has identified several different chemical scaffolds that might be worth further investigation in the Top1 inhibition and anticancer field." (PMID 21966440, 2011). "This is also the first report on the haplotype distribution of TOP1 in a panel of human tumours." (PMID 16983402, 2006). "We explored, in the NCI panel of 60 human tumour cell lines, whether polymorphic variations in the TOP1 gene could explain differences in drug sensitivity." (PMID 16983402, 2006). "Camptothecins are DNA topoisomerase I-directed anti-tumour drugs with a novel mechanism of action." (PMID 7640225, 1995). "Similarly, TOP1 expression was significantly reduced in the tumor in the knockdown groups." (PMID 39156107, 2024). "Additionally, we investigate the downstream effectors of TOP1 in CC cells and identify TOP1-mediated tumor-promoting inflammatory features, characterized by alterations in the expression of CXCLs, HMGB1, IL-6, and STAT3/5, as well as several T cell regulatory genes." (PMID 39156107, 2024). "Notably, FASN and TOP1 are known as tumor promoting factors and biomarkers of a poor prognosis." (PMID 37587470, 2023). "Thus, we investigated whether inhibition of TOP1 degradation using NEDD8-activating enzyme inhibitor MLN4924 could result in better anti-tumor effects of 10-HCPT in HNSCC treatment." (PMID 37689760, 2023). "Therefore, the inhibition of TDP1 can sensitize tumor cells to the action of TOP1 poisons." (PMID 36982848, 2023). "Combination of Top1 poisons with immunotherapies is further supported by evidence that in breast cancer cells Topotecan induces IFN I signalling and upregulation of class I MHC genes, a potential mechanism for immune sensitization of tumours deficient of MHC antigens on membrane surface." (PMID 36114513, 2022). "Therefore, the addition of Tdp1 inhibitors to chemotherapeutic cocktails is a promising strategy for increasing the sensitivity of tumor cells to Top1 inhibitors, in particular Tpc, and reducing their overall toxicity to the body due to a lower therapeutic dose." (PMID 36615517, 2022). "Thus, our findings can potentially expand the application of both CX-5461 and TOP1 inhibitors such as topotecan in clinical trials to the 50% of HGSC patients who have HR-proficient tumours and to patients with HR-deficient tumours that have acquired chemotherapeutic resistance due to restored HR." (PMID 33173151, 2021). "Furthermore, enzymes not previously implicated in FP activity, including DNA topoisomerase 1 (Top1), were established as mediating FP anti-tumor activity." (PMID 32751071, 2020). "Additionally, some authors also proposed that a dual targeting topoisomerase might increase overall anti-tumor activity, given that top1 and top2 have overlapping functions in DNA metabolism." (PMID 26462155, 2015). "Maximal Top1 down regulation in responsive xenograft models was observed 4 to 7 hours post-treatment, suggesting that this may be the optimum time window to collect a post-dose tumor biopsy from patients." (PMID 23284638, 2012).